RNF13 (ring finger protein 13)
Diseases named in the same sentence as RNF13 in open-access papers:
RNF13 is named in the same sentence as 38 diseases in open-access papers, as found by Europe PMC text mining. Sharing a sentence is not in itself a finding about the gene and the disease. The quoted sentences say what the papers report.
melanoma (3 papers, 2015 to 2021). A malignant, usually aggressive tumor composed of atypical, neoplastic melanocytes. "Overexpression of the RNF13 enzyme is apparent in various human cancers, including basal cell carcinoma, melanoma, and ovarian carcinoma." (PMID 34465340, 2021). "The previous studies has shown that the overexpression of a wild‐type RNF13 in murine melanoma cell line (B16F10) restrained the colonization of tumor cells in the lung." (PMID 32250047, 2020). "In these experiments, we used conditioned media generated by culturing slices of melanoma bearing lung tissues from either RNF13-KO mice or their WT littermates as chemoattractants." (PMID 26197965, 2015). "B16F10 melanoma cells were injected into the dorsal tail vein of the RNF13-KO mice and their WT littermates, which resulted in increased metastasis in RNF13-KO mice bearing B16F10 cells for 14 days." (PMID 26197965, 2015). "Injection of B16F10 melanoma cells or LLC cells into the tail vein of mice enhanced pulmonary metastasis in RNF13-KO mice." (PMID 26197965, 2015). "Microarray analysis of multiple tumor samples suggested a link between RNF13 expression and various human tumors including melanoma." (PMID 26197965, 2015). "Taken together, our data indicate that host RNF13 may affect melanoma cell colonization in the lung by modulating the concentration of GM-CSF in the target organ, which may reduce the amount of B16F10 cells available for homing to the lung." (PMID 26197965, 2015). "The absence of host RNF13 lowered the concentration of GM-CSF in tumor bearing lungs, leading to enhanced invasion of melanoma cells and increased lung colonization." (PMID 26197965, 2015).
pancreatic cancer (3 papers, 2015 to 2022). "For example, RNF13 is an ER/Golgi membrane-associated E3, and overexpressed RNF13 increases the invasive potential and gelatinolytic activity of pancreatic cancer by increasing matrix metalloproteinase-9 (MMP9) activity." (PMID 30832692, 2019). "RNF13 is an E3 ubiquitin ligase, and its association with pancreatic cancer was previously reported by our lab." (PMID 26197965, 2015). "RNF13 cannot be detected in pancreatic ductal epithelial cells, whereas it is expressed in pancreatic carcinoma precancerous lesion (chronic pancreatitis and pancreatic intraepithelial neoplasia) and pancreatic ductal adenocarcinoma." (PMID 26197965, 2015). "In pancreatic cancer, the overexpression of WT, but not DN, RNF13 in MiaPaca-2 cells led to increased matrix metallopeptidase 9 (MMP-9) activity, suggesting that the Ub ligase activity of RNF13 promotes metalloprotease function and cell invasion." (PMID 35159190, 2022).
pancreatic ductal adenocarcinoma (3 papers, 2010 to 2022). An infiltrating adenocarcinoma that arises from the epithelial cells of the pancreas. "Our previous research in pancreatic ductal adenocarcinoma showed that RNF13 expression is significantly associated with histological grading." (PMID 26197965, 2015). "A study that included 72 pancreatic ductal adenocarcinoma (PDAC) patients showed that RNF13 was overexpressed in 30 tumor samples, and its expression was significantly associated with histological grading." (PMID 26197965, 2015). "Indeed, RNF13 expression is downregulated in uveal melanoma, while RNF13 expression was found to be significantly higher in pancreatic ductal adenocarcinoma (PDAC) than in normal, healthy pancreatic tissue." (PMID 35159190, 2022). "Finally, Rnf13 is a trans-membrane RING-type E3 ubiquitin ligase highly expressed in pancreatic ductal adenocarcinoma, but also expressed in chicken embryo brain and heart." (PMID 20937113, 2010).
acute myeloid leukemia (2 papers, 2022 to 2025). Acute myeloid leukemia (AML) is a group of neoplasms arising from precursor cells committed to the myeloid cell-line differentiation. "For instance, circ_RNF13 is downregulated in lung adenocarcinoma (LAD) and nasopharyngeal carcinoma (NPC), but it is upregulated in acute myeloid leukemia (AML) and pancreatic cancer (PC)." (PMID 36551703, 2022).
colorectal cancer (2 papers, 2022 to 2024). A primary or metastatic malignant neoplasm that affects the colon or rectum. "Circ_RNF13 and DEAD/H (Asp-Glu-Ala-Asp/His) box polypeptide 27 (DDX27) exhibit upregulation in colorectal cancer patient samples and cells." (PMID 39160596, 2024). "Circ_RNF13 contributes to the stabilization of TRIM24 by suppressing F-box and WD repeat domain containing 7 (FBXW7)-mediated TRIM24 degradation, thereby enhancing chemosensitivity in colorectal cancer." (PMID 39160596, 2024).
hepatocellular carcinoma (2 papers, 2021 to 2023). A malignant tumor that arises from hepatocytes. "Circular RNA RNF13 (circ-RNF13; ID: hsa_circ_0067717) is newly identified to be abnormally upregulated in hepatitis B virus (HBV)-associated hepatocellular carcinoma (HCC) patients." (PMID 33714261, 2021).
nasopharyngeal carcinoma (2 papers, 2021 to 2022). A carcinoma arising from the nasopharyngeal epithelium. "Circ-RNF13 prolongs the half-life of SUMO2 by binding to the 3′ untranslated regions (3′-UTR) of SUMO2 gene, which leads to sumoylation of GLUT1 and ubiquitination to regulate the AMPK-mtor pathway, ultimately promoting proliferation and metastasis of nasopharyngeal carcinoma (NPC)." (PMID 34881248, 2021).
atherosclerosis (1 paper, 2020). A disease characterized by the build-up of fatty material and calcium deposition in the arterial wall resulting in partial or complete occlusion of the arterial lumen. "But few studies investigated the role of RNF13 in atherosclerosis or FCs." (PMID 33240650, 2020). "GLRX, RNF13, and ABCA1 might be potential targets for atherosclerosis treatment." (PMID 33240650, 2020).
colon cancer (1 paper, 2015). "Human tissue microarray analysis also suggested an association between RNF13 expression and human colon cancer development, as the RNF13 protein is expressed at higher levels in human colon cancer samples than in control samples." (PMID 26197965, 2015).
epilepsy (1 paper, 2024). A brain disorder characterized by episodes of abnormally increased neuronal discharge resulting in transient episodes of sensory or motor neurological dysfunction, or psychic dysfunction. "ERAD is known to be altered in some genetic diseases with epilepsy, including familial encephalopathy with neuroserpin inclusion bodies (FENIB) and RNF13-associated infantile neurodegeneration." (PMID 38731820, 2024).
Epileptic encephalopathy (1 paper, 2024). A condition in which epileptiform abnormalities are believed to contribute to the progressive disturbance in cerebral function. "Heterozygous RNF13 gain-of-function variants have been associated with congenital microcephaly, epileptic encephalopathy, blindness, and failure to thrive." (PMID 38816452, 2024).
Hepatic steatosis (1 paper, 2023). Steatosis is a term used to denote lipid accumulation within hepatocytes. "Analysis of lipometabolic gene expression also validated the impact of RNF13 on hepatic steatosis." (PMID 37857628, 2023). "Overall, RNF13 suppression aggravates HFD-induced insulin resistance, hepatic steatosis, and liver injury." (PMID 37857628, 2023).
Insulin resistance (1 paper, 2023). Increased resistance towards insulin, that is, diminished effectiveness of insulin in reducing blood glucose levels. "Consistent with the phenotypes in the HFD-induced model, Rnf13 knockout intensified insulin resistance, hepatic steatosis, and liver injury in the HFHC-induced NASH model." (PMID 37857628, 2023). "Second, given that Rnf13 gene disruption in hepatocytes exhibits significant impacts on insulin resistance and blood glucose, whether RNF13 participates in the regulation of insulin signaling pathways in other metabolic organs merits further investigation." (PMID 37857628, 2023).
lung adenocarcinoma (1 paper, 2013). A carcinoma that arises from the lung and is characterized by the presence of malignant glandular epithelial cells. "CDK13, BMP1, RNF13, MAT2A, CHRNA4 are also among the genes in Merged-module whose over-expression has been reported in different cancers, however, their over-expression has been demonstrated in lung adenocarcinoma in this study." (PMID 23874428, 2013).
lung carcinoma (1 paper, 2015). "In mice bearing LLC cells for 27 days, the eight RNF13-KO mice developed lung cancer." (PMID 26197965, 2015).
neuroblastoma (1 paper, 2011). Neuroblastoma (NB) is the most common solid, extracranial childhood tumor. "In addition, RNF13 expression is increased in differentiating rat B35 neuroblastoma cells, and overexpression of RNF13 promotes neurite extension in rat PC12 pheochromocytoma cells, suggesting an involvement of RNF13 in neuronal development." (PMID 24957874, 2011).
Parkinson disease (1 paper, 2022). A progressive degenerative disorder of the central nervous system characterized by loss of dopamine producing neurons in the substantia nigra and the presence of Lewy bodies in the substantia nigra and locus coeruleus. "A recent study demonstrated that silencing RNF13 could alleviate the symptoms in a Parkinson’s disease mouse model." (PMID 35159190, 2022). "Overall, this study suggests that reducing the activation of the IRE1α-TRAF2-ASK1-JNK pathway by silencing RNF13 might be beneficial to alleviate some of the motor dysfunction and to prevent the dopaminergic neuron damage in a Parkinson’s disease mouse model." (PMID 35159190, 2022).
retinal detachment (1 paper, 2025). An eye emergency condition which may lead to blindness if left untreated. "The downregulation of RNF13 may correlate with the temporary suppression of retinal pigment epithelial (RPE) function and the initiation of immune responses, both of which are critical for cellular function and immune regulation following retinal detachment." (PMID 41007990, 2025).
rheumatoid arthritis (1 paper, 2024). A chronic, systemic autoimmune disorder characterized by inflammation in the synovial membranes and articular surfaces. "Furthermore, peripheral blood mononuclear cells (PBMCs) from patients with rheumatoid arthritis (RA) show increased RNF13 levels and decreased LAMP‐1 expression." (PMID 39031743, 2024).
steatosis (1 paper, 2023). Increased lipid within the cytoplasm of cells. "Rnf13 knockout in hepatocytes exacerbate insulin resistance, steatosis, inflammation, cell injury and fibrosis in the liver of diet-induced mice, which can be alleviated by Rnf13 overexpression." (PMID 37857628, 2023).
cancer (8 papers, 2013 to 2025). A tumor composed of atypical neoplastic, often pleomorphic cells that invade other tissues. "RING finger protein 13 (RNF13) is a novel E3 ubiquitin ligase whose expression is associated with cancer development." (PMID 26197965, 2015). "Analysis of the causes of death showed that the rate of cancer-related death was similar between RNF13-KO and WT mice." (PMID 26197965, 2015). "RNF13 mutations were identified across different cancer types." (PMID 34831286, 2021). "Furthermore, altered RNF13 expression has been linked to cancer." (PMID 35159190, 2022). "Emerging evidence indicates that circ_RNF13 exerted an oncogenic or tumor-suppressive role, depending on the cancer type." (PMID 36551703, 2022). "For instance, hundreds of single-nucleotide variation (SNV) mutations for RNF167, RNF13, and ZNRF4 have been reported in cancer." (PMID 35159190, 2022). "For instance, consultation of the BioMuta dataset, which catalogues single-nucleotide variations in cancer, currently displays more than 60 unique variations within the coding sequence of the human RNF13 gene." (PMID 34831286, 2021). "RING finger protein 13 (RNF13) is a newly identified E3 ligase reported to be functionally significant in the regulation of cancer development, muscle cell growth, and neuronal development." (PMID 24563216, 2014). "Circ_RNF13, also known as hsa_circ_0001346, is dysregulated in different types of cancer." (PMID 36551703, 2022). "RNF13, which acts as a ubiquitin ligase, participates in cancer invasion and metastasis." (PMID 34465340, 2021). "Emerging evidence suggests that RNF13 functions in cancer development." (PMID 26197965, 2015). "However, our results did not exclude the possibility that RNF13 could function under pathological conditions by affecting the disease process, or its involvement in processes associated with cancer development." (PMID 26197965, 2015).
tumor (8 papers, 2015 to 2025). "One study investigated some of the RNF13 variants identified in tumor samples." (PMID 35159190, 2022). "In addition to the identification of the RNF13 variants in tumor samples, some RNF167 variants were identified and characterized as well." (PMID 35159190, 2022). "We demonstrated that circ_RNF13 was elevated in CRC tumor samples and cells, which was in line with the circRNA expression profile." (PMID 36551703, 2022). "Silencing of circ_RNF13 decreased the tumor size, volume, and incidence, compared with the control group." (PMID 36551703, 2022). "An expression profile has illustrated that circ_RNF13 is elevated in CRC tumor samples, compared with its normal counterparts." (PMID 36551703, 2022). "Tumor growth was induced in both sh-circ-RNF13 and sh-NC groups, while tumor volume and weight were lowered in sh-circ-RNF13 group." (PMID 33714261, 2021). "RNF13-KO mice showed a larger metastatic area in the lung and a heavier tumor-bearing lung tissue than their WT littermates." (PMID 26197965, 2015). "Collectively, our results suggest that host RNF13 affects the concentration of GM-CSF in tumor-bearing lungs, leading to a reduction in the colonization of metastatic tumor cells in the lung." (PMID 26197965, 2015). "Data quantification indicated that the number of either single tumor cells (2 days) or micrometastases (4 days) was higher in RNF13-KO mice than in their WT littermates." (PMID 26197965, 2015). "In the present study, we established a B16F10 experimental metastatic model in RNF13-knockout (KO) mice and tracked the changes of tumor cells during this experimental metastasis." (PMID 26197965, 2015). "Among these RNF13-KO mice, 1/8 died from the tumor metastasis, and 1/8 developed pulmonary, diaphragmatic, and mesenteric metastasis, while no tumors were detected in other tissues besides the lung in six WT mice." (PMID 26197965, 2015). "The results showed that GM-CSF concentration was significantly decreased in RNF13-KO tumor bearing lungs." (PMID 26197965, 2015). "In addition, circ_RNF13 was positively correlated with tumor size, distant metastasis, lymph metastasis, and TNM stage." (PMID 36551703, 2022). "An expression profile has revealed that circ_RNF13 is upregulated in CRC tumor samples." (PMID 36551703, 2022). "Circ_RNF13 was elevated in CRC tumor samples, compared with their normal counterparts." (PMID 36551703, 2022). "Circ_RNF13 functions as either an oncogene or a tumor suppressor in different tumors." (PMID 36551703, 2022). "Pathological sections showed that tumor number was increased in RNF13-KO mice." (PMID 26197965, 2015). "In the present study, we confirmed that host RNF13 could block the colonization of metastatic tumor cells." (PMID 26197965, 2015). "Our previous work suggested a link between RNF13 and tumor progression." (PMID 26197965, 2015). "Therefore, we investigated whether deletion of host RNF13 may affect tumor cell proliferation and lead to enhanced metastasis." (PMID 26197965, 2015). "To study the roles of circ_RNF13 and DDX27 in CRC, we first examined their expression in CRC tumor samples." (PMID 36551703, 2022). "Subsequent experiments revealed that silencing of circ_RNF13 enhanced the chemosensitivity to L-OHP or CPT-11 in which the tumor size and volume were notably reduced in sh-circ_RNF13+L-OHP or sh-circ_RNF13+CPT-11 groups, compared with the corresponding controls." (PMID 36551703, 2022). "In contrast, RNF13 knockout mice implanted with a pulmonary metastatic cancer cell model did not have a difference in tumor size when compared to their WT littermates, but the WTs exhibited a larger metastatic area in the lung." (PMID 35159190, 2022). "As a result, blocking circ-RNF13 enhanced the apoptosis rate of Huh7-HBV and Hep3B-HBV cells, but inhibited cell proliferation, colony formation, migration, and invasion in vitro, along with suppressed tumor growth in vivo." (PMID 33714261, 2021).
tumor (continued). "In short-term experiments, the number of fluorescently-labeled B16F10 cells increased remarkably in RNF13-KO lungs at early time points, whereas clearance of tumor cells from the blood was not affected." (PMID 26197965, 2015). "Whereas the molecular mechanism of RNF13 regulation of GM-CSF concentration is not yet understood, it is well known that invasion is the first step to metastasis formation while the host microenvironment is key to establishing the final fate of the tumor cells." (PMID 35159190, 2022). "Furthermore, we found that the lack of host RNF13 did not promote in situ LLC tumor growth." (PMID 26197965, 2015).
infection (1 paper, 2024). The state of being infected such as from the introduction of a foreign agent such as serum, vaccine, antigenic substance or organism. "To assess the role of RNF13 in the host innate response to infection against gram‐negative or gram‐positive bacteria, we intraperitoneally injected Rnf13−/− mice with Escherichia coli (E. Coli) and L. M., respectively." (PMID 39031743, 2024).
RNF13 also shares sentences with these, for which no sentence is quoted: AIDS (1 paper); autoimmune disease (1); basal cell carcinoma (1); chronic pancreatitis (1); Failure to thrive (1); familial encephalopathy with neuroserpin inclusion bodies (1); genetic diseases (1); inflammation (1); malaria (1); mental retardation (1); microcephaly (1); nonalcoholic steatohepatitis (1); ovarian carcinoma (1); pheochromocytoma (1); uveal melanoma (1).